RNU1-134P (RNA, U1 small nuclear 134, pseudogene)
Gene: Small nuclear RNA gene on chromosome 20 (63,908,955 to 63,909,119, forward strand). Ensembl gene ENSG00000199805.
Homologues: Orthologues: chimpanzee U1 (98% identical), macaque U1 (90% identical), rabbit U1 (87% identical), mouse Gm25818 (87% identical). Paralogues in human: RNU1-1 (90% identical), RNU1-2 (90% identical), RNU1-27P (90% identical), RNU1-28P (90% identical), RNU1-3 (90% identical), RNU1-4 (90% identical), RNVU1-18 (90% identical), RNVU1-29 (90% identical), RNVU1-31 (90% identical), U1 (90% identical), RNVU1-28 (90% identical), RNVU1-7 (90% identical), and 134 more.